IL6 (interleukin 6)
Diseases named in the same sentence as IL6 in open-access papers (continued):
Sharing a sentence is not in itself a finding about the gene and the disease.
breast cancer (continued). "High IL-6 serum levels are associated with poor prognosis in breast cancer patients." (PMID 32005799, 2020). "Moreover, cancer-associated fibroblasts isolated from breast cancer metastatic sites enhance cancer cell growth and invasiveness in an IL-6-dependent manner." (PMID 31557902, 2019). "For instance, loss of PTEN in a HER2-overexpression genetic background or the trastuzumab resistance in breast cancer cells has been linked to activation of the IL-6/STAT-3/NF-κB inflammatory loop, which induced an EMT phenotype and expansion of the CSC population." (PMID 31417869, 2019). "IL6 could induce tamoxifen resistance in luminal breast cancer, and was implicated in CSC maintenance and progenitor-enriched mammosphere formation." (PMID 31709178, 2019). "Cancer-associated fibroblasts, an important IL-6 source, strongly related to tumor growth and therapy resistance which can be targeted for the development of potential drugs on treatment and prevention of breast cancer." (PMID 31398937, 2019). "In breast cancer, high IL-6 is associated with poor prognosis." (PMID 30154786, 2018). "Moreover, the score was positively associated with inflammatory cytokines, including CRP and IL-6, which were also positively associated with the risk for overall mortality in patients with breast cancer." (PMID 30111758, 2018). "Some studies show that fatigue in breast cancer was associated with higher levels of IL-6 13,14." (PMID 30774833, 2018). "Furthermore clinical studies demonstrated increased serum concentrations of IL-6 in breast cancer patients are strongly associated with tumor stage and poor prognosis." (PMID 29721190, 2018). "Moreover, the mRNA levels of HBXIP were positively associated with those of IL-6 in 34 ER+ clinical breast cancer tissues." (PMID 29471853, 2018). "The downregulation of IL-6 and other DEGs is associated with highly malignant mammary carcinomas." (PMID 29593668, 2018). "We hypothesized that IL-6: rs1800795 SNPs within the host genome of breast cancer patients are associated with a greater risk of developing distant metastases." (PMID 28732081, 2017). "The association between high levels of IL-6 and lower survival was also observed in patients with renal cell carcinoma, chronic lymphocytic leukemia, gastric carcinoma, prostate cancer, gastrointestinal cancer and breast cancer." (PMID 28715437, 2017). "The pleiotropic cytokine IL-6 has been implicated in several cancer forms, including breast cancer." (PMID 29387062, 2017). "We hypothesized that SNPs of the IL-6 promoter at rs1800795 in breast cancer patients are associated with distant metastases." (PMID 28732081, 2017). "In addition, a recent meta-analysis (13 articles with 3,224 patients) showed that IL-6 expression is associated with a poor prognosis in breast cancer." (PMID 28732081, 2017). "In addition, the IL-6/YAP signaling has been shown to be associated with increased stemness in breast cancer." (PMID 28241877, 2017). "In addition, clinical studies have shown increased circulating levels of IL-6 in patients with breast cancer as well as an association between higher circulating levels and more advanced stages of disease including metastasis." (PMID 28732081, 2017). "We carried out a case-control study to prospectively assess whether pre-diagnostic levels of CRP, TNF-α, IL-6, leptin, and adiponectin in plasma are associated with risk of developing breast cancer." (PMID 28983080, 2017). "It is interesting to speculate why obese patients with increased levels of IL-6 have a predisposition to developing ER+ breast cancers specifically." (PMID 26884646, 2016). "IL-6 is significantly elevated in lung and breast cancer patients, associated with poor prognosis." (PMID 27107418, 2016). "Of note is that IL-6 according to previous reports may act both as an anti-inflammatory and a pro-inflammatory cytokine and has previously been implicated with breast cancer." (PMID 27391324, 2016).
breast cancer (continued). "IL-6 overexpression and its receptors may be associated with increased proliferation of breast cancer cells." (PMID 27538520, 2016). "In addition, an inverse and significant association with breast cancer was observed for the second tertile of IL-6, 0.72 (0.53–0.98)." (PMID 27391324, 2016). "A third study demonstrated that expression of IL-6 is approximately 100-fold higher in cancer-associated fibroblasts compared to normal fibroblasts, suggesting that IL-6 may potentiate breast cancer invasiveness." (PMID 26828520, 2016). "Additionally, the JAK2/STAT3/IL6 pathway has been shown to be required for the growth of CD44-CD24+ breast cancer cells, cell surface markers believed to be associated with breast TICs." (PMID 27764181, 2016). "Importantly, the IL-6/STAT3/NF-κB pro-inflammatory circuit was also active in cancer-associated fibroblasts isolated from breast cancer patients." (PMID 27248826, 2016). "Together these results suggest that trastuzumab resistance in PTEN deficient HER2+ breast cancer results in the EMT to transforms PTEN deficient HER2+ breast cancer to a triple negative phenotype that is dependent upon the IL-6/STAT3/NF-κB signaling axis for survival and self-renewal of CSCs." (PMID 26522776, 2015). "Furthermore, high IL-6 levels have been associated with poor clinical outcome in breast cancer patients." (PMID 26515594, 2015). "In addition, LPS treatment was shown to increase the levels of IL-6 and IL-8, which are closely associated with the invasiveness of breast cancer cells." (PMID 25691060, 2015). "Interleukin-6 is produced by both inflammation-associated macrophages and breast cancer cell-associated fibroblasts, and the stimulation of both ER-positive and ER (triple)-negative breast cancer cell invasion by co-culture with adipose stromal cells was shown to be mediated by IL-6." (PMID 26516917, 2015). "Concurrently, macrophages treated with breast cancer-derived exosomes caused significant increases in NF-κβ activation and production of inflammatory cytokines (including IL-6 and TNFα) compared to exosomes from normal breast cells through exosomal binding to the Toll-like receptor 2 (TLR2)." (PMID 26601108, 2015). "Several IL6 single nucleotide polymorphisms have been associated with breast cancer prognosis, but the impact may differ depending on tumour oestrogen receptor (ER) status." (PMID 25305747, 2014). "An IL6 haplotype that consists of the SNPs rs1800797 (-596A > G), rs1800796 (-572G > C), -373 [10A/11 T], and rs1800795 (-174G > C) was associated with reduced disease-free survival among breast cancer patients." (PMID 25305747, 2014). "In addition, elevated levels of IL-6 have been linked to poor prognosis in breast cancer patients and IL-6 plays vital roles not only in tumorigenesis, but also in inflammatory diseases including RA." (PMID 25405203, 2014). "Moreover, IL-6 expression has been associated with disease severity in cervical, head and neck and breast cancer patients." (PMID 25400927, 2014). "It seems plausible that variations in the IL6 gene could have effects on cell growth and alter MD and eventually breast cancer risk." (PMID 23762340, 2013). "According to our findings, Syndecan-1 silencing in triple-negative MDA-MB-231 breast cancer cells inhibited proinflammatory signaling via downregulation of relevant receptors and ligands (IL-6/IL6-R/CCL20), which was linked to reduced constitutive activation of NFkB and STAT3." (PMID 24392029, 2013). "Genetic variations in IL6 may be associated with MD and therefore may be an indicator of breast cancer risk in premenopausal women." (PMID 23762340, 2013). "In addition, IL-6 mRNA was detected only in basal-like breast carcinoma tissues, an aggressive breast carcinoma variant that displays stem cell features." (PMID 22235336, 2012). "Hence, IL-6 elicits its own mRNA expression and proximal promoter loss of methylation in breast cancer cells." (PMID 21092249, 2010).
breast cancer (continued). "Furthermore, high IL-6 levels have been linked to a poor prognosis in patients with advanced breast cancer, the pathogenesis of inflammatory breast cancer, and resistance to chemotherapy." (PMID 17531096, 2007). "Since the common −174 G/C polymorphism has been linked to reduced production of IL-6, we hypothesised that this genetic variant may be associated with a more aggressive breast cancer phenotype." (PMID 14735187, 2004). "In light of the earlier studies linking serum and tissue IL-6 levels to breast cancer outcomes, the aim of the present study was to investigate for possible associations between the −174 G/C IL-6 polymorphism and phenotypic characteristics of breast cancer." (PMID 14735187, 2004). "This could explain the favourable prognosis associated with the presence of tumour IL-6 in early-stage breast cancer and the poor survival associated with high serum IL-6 levels in this series of metastatic breast cancer patients." (PMID 12771987, 2003). "Our data demonstrate that IL-6 knockdown attenuated solid stress-induced cell migration, suggesting that the observed upregulation of IL-6 protein and secretion levels in compressed breast cancer cells could play an underlying role in solid stress-induced cancer cell migration." (PMID 40371393, 2025). "Additionally, the research indicates that IL-6 is a pro-inflammatory cytokine, and elevated levels of IL-6 are associated with the occurrence and progression of various cancers, including breast cancer, colorectal cancer, gastric cancer, ovarian cancer, and others." (PMID 37381018, 2023). "Furthermore, TAMs activate the NF-κB/STAT3/ERK signaling pathway in tumor cells by secreting pro-inflammatory cytokines such as TNF-α and IL-6, which are responsible for the phosphorylation and activation of ERα, causing endocrine therapy resistance of breast cancer." (PMID 37900137, 2023). "Therefore, we next tried to investigate whether there was an association between PDGF signaling and IL-6 in HER2+ breast cancer through observing the alteration of IL-6 expression by PDGFR activation." (PMID 36979654, 2023). "Furthermore, TGFβ increases Jagged 1 expression in metastatic breast cancer cells, and Jagged 1 activates NOTCH1 in osteoblasts, causing IL-6 expression to support the survival of metastatic breast cancer cells and leading to the development of osteoclasts mediating bone breakdown." (PMID 36517618, 2022). "Additionally, IL-6 and leptin produced by adipocytes are known to promote angiogenesis, invasion, and metastasis, and we have previously shown that intratumoral angiogenesis is associated with metastatic recurrence in breast cancer." (PMID 34071012, 2021). "Recently, a publication provided a novel sight for breast cancer treatment that KPNA2 and IL-6 associated inflammation could facilitate c-Myc nuclear translocation and regulate breast cancer development, and this similar mechanism has also been verified in our prostatic cancer cells." (PMID 34657603, 2021). "While serum inflammatory biomarkers may not be an effective means of identifying or monitoring such patients, these findings lend further support to targeting the IL-6/JAK/STAT pathway in some patients with HER2+ breast cancer who harbor the high-risk IL-6 genotype." (PMID 33483516, 2021). "However, the prognostic role of IL-6 and IL-8 association in breast cancer may differ according to breast cancer subtype." (PMID 34445170, 2021). "IL-6 and TNFa are two major cytokines that could involve in systemic inflammation and acute-phase reactions; also, their serum levels have been shown to increase in obese individuals and are consistently associated with the development of breast cancer." (PMID 33517609, 2021).
breast cancer (continued). "In addition to the vasculature, this putative connection between IL-6 and PI3KαH1047R raises implications for paracrine crosstalk with resident immune, adipocyte, and mesenchymal cells that advances breast cancer progression in patients harboring PI3Kα activating mutations." (PMID 32632100, 2020). "Notably, curcumin has demonstrated potent anti-STAT3 activity through STAT3 cysteine modification that prevents phosphorylation and it has been found to inhibit proliferation breast cancer and esophageal squamous cell carcinoma, with the latter being associated with significant decreases in IL-6." (PMID 31842362, 2019). "IL6 was also previously shown to be one of the most significantly increased inflammatory cytokines in African-American breast cancer patients compared to White patients, and high plasma IL6 levels were identified as a breast cancer risk factor in African-American women." (PMID 31511085, 2019). "Clinical studies have revealed that a high serum expression level of IL-6 in patients is associated with advanced tumor stages in various cancers (multiple myeloma, non-small cell lung carcinoma, colorectal cancer, renal cell carcinoma, prostate cancer, breast cancer and ovarian cancer)." (PMID 30134951, 2018). "Moreover, IL-6 is associated with a poor prognosis in breast cancer patients." (PMID 30134951, 2018). "In this study, serum carotenoids were inversely associated with IL-6 and sTNFR-II, which is notable, as elevations in these markers of systemic inflammation have been associated with alterations in brain structure and function in breast cancer patients and survivors." (PMID 30126098, 2018). "Indeed, some authors believed that excessive sleep might lead to elevated levels of systemic inflammation and increase some inflammatory biomarkers, such as CRP and IL-6, which might predispose an individual to breast cancer." (PMID 29130041, 2017). "Interleukin-6 could induced malignant transformation of stem cells in association with enhanced signaling of Stat331 and myeloid-derived cells endowed stem-like qualities to breast cancer cells through IL6/STAT3 and NO/NOTCH cross-talk signaling." (PMID 27833137, 2016). "Moreover, the expression of IL-6 in breast cancer is associated with poor prognosis." (PMID 25147739, 2014). "In addition to these tumors, increased IL-6 signaling is preferentially found in basal-like breast cancers and high-grade tumors and is associated with a poor response to chemotherapy, increased distant metastasis in xenograft animal models and decreased metastasis-free survival in patients." (PMID 24021059, 2013). "Moreover, systemic chronic inflammation mediated by IL-6 may increase the risk of breast cancer recurrence and affect its prognosis." (PMID 23819063, 2013). "Elevated IL-6 levels correlate with poor prognosis in breast cancer patients and persistent IL-6/STAT3 activation promotes tumour proliferation, metastasis, angiogenesis and therapy resistance." (PMID 42316398, 2026). "Interleukin-6 (IL-6) signalling is a key driver of breast cancer progression, activating pro-survival, pro-inflammatory and metastatic programs through its receptors, IL-6R and GP130." (PMID 42316398, 2026). "BHLHE40-AS1, which lies antisense to the BHLHE40 promoter, functions independently of BHLHE40 and has been shown to modulate IL-6/STAT3 signaling in early-stage breast cancer, contributing to an immunosuppressive TME that promotes tumor progression." (PMID 41501810, 2026). "Together, these findings support the preclinical development of huE17 and huNA7 and the potential of dual IL-6R and GP130 targeting in IL-6-driven breast cancer." (PMID 42316398, 2026). "Overall, the evidence firmly supports IL-6 as a key driver of tumor progression and a predictor of poor prognosis in breast cancer." (PMID 41007766, 2025). "The results indicated that mind–body exercise significantly reduced the IL-6 levels in breast cancer patients (SMD = −0.30, 95% CI [−0.56, −0.03], p = 0.03)." (PMID 41221238, 2025).
breast cancer (continued). "Literature has reported that higher-intensity AE is linked to lowered levels of CRP, IL-6, and TNF-α, and this has been determined in breast cancer." (PMID 41480347, 2025). "A 2018 study found that obese postmenopausal breast cancer survivors can reduce inflammation (IL-6 and TNF-α) through a combination of resistance and aerobic exercise training." (PMID 40584290, 2025). "Chronic inflammation, driven by higher levels of inflammatory cytokines such as TNF-α and IL-6 as well as telomere shortening, significantly contributes to the aging characteristics of breast cancer survivors." (PMID 40075712, 2025). "Despite the presence of differences in subpopulations, the majority of these cells produce interleukin 6 (IL-6), a key factor in the development of immune resistance in breast cancer (BC) patients and the promotion of thyroid cancer (TC) cell proliferation." (PMID 41301715, 2025). "In breast cancer, CAFs secrete IL-6 to activate Notch signaling in cancer cells, which also mediates the effects of estrogen G protein-coupled receptor (GPER) signaling in both cancer cells and CAFs." (PMID 41050674, 2025). "This indicates that autophagy-dependent IL-6 secretion effectively promotes the malignant progression of breast cancer through the STAT3 pathway." (PMID 39893499, 2025). "A parallel therapeutic benefit has been observed in breast cancer, where simvastatin‐mediated suppression of senescent cell‐derived IL‐6 secretion mitigates chemoradiotherapy‐induced endocrine resistance, ultimately improving treatment outcomes." (PMID 41427020, 2025). "Notch ligand Jagged1, expressed by breast cancer cells, stimulates the release of interleukin-6 (IL-6) from osteoblasts, which in turn promotes tumor growth and osteoclast activation." (PMID 40444046, 2025). "The molecular mechanism of IL-6 in breast cancer is likely context-dependent, involving interactions between the STAT3-dependent pathway and the growth-promoting MAPK/PI3K pathway." (PMID 41226910, 2025). "Here, we found IL-6’s involvement in solid stress-induced metastatic phenotype alterations of breast cancer cells." (PMID 40371393, 2025). "Mechanistically, M2 enhances tumor survival via pathways like CCL2/PI3K/Akt/mTOR in breast cancer, IL-6/STAT3 in colon and pancreatic cancers, and CHI3L1 in gastric/breast cancers." (PMID 40940877, 2025). "miR-21 is elevated in canine mammary tumors and positively correlates with gene expression of IL-6 and TNF-α and also with the proliferation index (Ki67 index) of tumour cells." (PMID 40028181, 2025). "The effect of recombinant human interleukin-6 (rhIL-6) on hematopoiesis, biochemical parameters, and other cytokines was evaluated in a phase I-II clinical study in 20 patients with breast cancer or non-small cell lung cancer." (PMID 41516250, 2025). "A total of 5 RCTs included 643 breast cancer patients to compare the differences in IL-6 levels between the mind–body exercise group and the control group." (PMID 41221238, 2025). "The aim of this study was to elucidate the contribution of IL‐6 to eribulin resistance using eribulin‐resistant breast cancer cell lines developed through long‐term exposure to eribulin." (PMID 41189442, 2025). "In postmenopausal women with early breast cancer, longitudinal studies reported short-term increases of 15–48% in IL-6, IL-8, IFN-γ, TNF-α, and IL-10 after adjuvant chemotherapy, returning toward baseline within 6–12 months." (PMID 41153842, 2025). "As a potent pro-inflammatory cytokine, IL-6 is overexpressed in various cancers, including breast cancer, where abnormal activation of the IL-6/JAK/STAT3 pathway has been documented." (PMID 40104495, 2025). "Nobiletin inhibits breast cancer cell migration and invasion by suppressing the IL-6-induced ERK-STAT and JNK-c-JUN pathways." (PMID 40328750, 2025). "The combination of biomarkers, including IL-6 and ER, facilitates the identification of breast cancer subtypes with distinct characteristics and biological behaviors." (PMID 40558287, 2025).